HMMR-AS1 (HMMR antisense RNA 1)
Gene: Long non-coding RNA gene on chromosome 5 (163,483,065 to 163,494,058, reverse strand). Ensembl gene ENSG00000251018.
Diseases named in the same sentence as HMMR-AS1 in open-access papers:
HMMR-AS1 is named in the same sentence as 6 diseases in open-access papers, as found by Europe PMC text mining. Sharing a sentence is not in itself a finding about the gene and the disease. The quoted sentences say what the papers report.
breast carcinoma (1 paper, 2022). "Among them, HMMR-AS1 is a recently discovered lncRNA, which is widely expressed in a variety of tumors, such as epithelial ovarian cancer, lung adenocarcinoma, radiosensitizes glioblastoma, and breast cancer." (PMID 35322735, 2022).
glioma (1 paper, 2021). A benign or malignant brain and spinal cord tumor that arises from glial cells (astrocytes, oligodendrocytes, ependymal cells). "Results showed that HMMR-AS1 abundance was increased more than 2.8-fold in glioma cells compared with NHA cells." (PMID 34719318, 2021).
tumor (1 paper, 2019). "HMMR-AS1 knockdown inhibits LUAD cell proliferation and tumor growth, whereas HMMR-AS1 overexpression promotes LUAD cell proliferation." (PMID 31128573, 2019).
HMMR-AS1 also shares sentences with these, for which no sentence is quoted: epithelial ovarian cancer (1 paper); glioblastoma (1); lung adenocarcinoma (1).